CDH3 (cadherin 3)
Diseases named in the same sentence as CDH3 in open-access papers (continued):
Sharing a sentence is not in itself a finding about the gene and the disease.
tumor (165 papers, 2005 to 2025). "CDH3 expression is significantly upregulated in various cancers, and is associated with poor prognosis and increased tumor invasiveness." (PMID 40227353, 2025). "Collectively, these findings suggest a strong association between CDH3 expression and tumor initiation and progression." (PMID 40227353, 2025). "Our analyses revealed a tumor-specific loss of CDH3 mRNA expression, CDH3 DNA hypermethylation, and loss of distal tubular and collecting duct CDH3 protein expression in RCC." (PMID 38003666, 2023). "Both the UPF approach and lumosVar 2.0 detected the eighteenth level-1 hotspot which was a CDH3 truncating mutations with high allele fractions in the tumor and low in the adjacent normal." (PMID 30949446, 2019). "Increased CDH3 expression has been associated with tumor aggressiveness, being a good indicator of clinical outcome." (PMID 20799942, 2010). "Our immunohistochemical examination of CDH3 expression revealed a significant loss of its signal in cancerous tissues, while immunopositivity was seen in noncancerous areas adjacent to the tumor site and in specimens from tumor-free kidneys." (PMID 38003666, 2023). "P-cadherin, encoded by the CDH3 gene, exerts a similar function but is mainly present in tumours." (PMID 37372088, 2023). "Globally, these genome‐wide analyses suggest that CDH3/P‐cadherin might be associated with pro‐tumor gene expression signatures that are known to be critical in GBM signaling." (PMID 34919784, 2022). "The most strongly elevated cadherin after the WNT/β-catenin pulse, CDH3, was reported to correlate with the loss of an epithelial phenotype of tumor cells upon gaining the ability to migrate and invade other tissues, while CHD3 suppression apparently reversed this phenotype." (PMID 33195222, 2020). "CDH3 was expressed by numerous normal organs and, thus, is not a viable vaccine target, however, the correlation between plasma and tumor CDH3 levels suggests CDH3 may have value as a diagnostic or prognostic marker." (PMID 29142905, 2017). "Interestingly, CDH3 sub-cellular distribution was altered in tumor cells, with a predominant loss of membrane immunoreactivity." (PMID 26771841, 2016). "This study demonstrates that CDH1, CDH2, and CDH3 are significantly upregulated in NSCLC and are associated with tumor progression, poor prognosis, and advanced disease stages." (PMID 40860670, 2025). "Notable examples within this intersecting group of genes included CDH3, ETV4, ESM1, and KRT80, all previously implicated in CRC progression and tumor microenvironment modulation." (PMID 40722723, 2025). "In contrast, CDH3 and the tumor markers CA 24-2, CA 19-9, CA 72-4, and CEA (P<0.001) were associated with the occurrence of distant metastasis of CRCs." (PMID 39247592, 2024). "After induction of biochemical gradient stromal-derived factor 1 (SDF1), single cell sequencing analysis of tumor clusters revealed 9 different cell population types and 1 primary cluster of leader cells with differential expression of Cadherin-3 (CDH3)." (PMID 39207729, 2024). "The hub genes of the network included SLC2A1 (solute carrier family 2 member 1), CDH3 (cadherin 3), and EFHD2 (EF-hand domain family member D2), whose expression increased with tumor stage and was associated with a lower survival rate." (PMID 39199659, 2024). "In agreement with this, IHC staining demonstrated higher expression of CDH3, as indicated by brownish yellow staining, in normal tissue than tumor tissue." (PMID 39247592, 2024). "We demonstrate CHAI’s practical use case by identifying a leader tumor cell cluster enriched with CDH3." (PMID 39207729, 2024). "In PDAC, cooperation with cadherin-3 prevents CDH-1 from negatively affecting tumor growth and positively enhances tumor aggressiveness and invasiveness." (PMID 39123454, 2024). "siRNA-induced suppression of CDH3 expression modulated the invasion characteristics of tumor cells in the impedance-based real-time cellular analysis." (PMID 38003666, 2023).
tumor (continued). "The secretion of two key molecules in EMT, vimentin and cadherin 3/11, was increased, while proteins involved in tumor immune escape, cell cycle and DNA damage were also increased to varying extent." (PMID 37649614, 2023). "The possible contribution of CDH3 to tumor cell invasiveness was tested in a functional assay using siRNA-based suppression of CDH3 expression and subsequent real-time impedance analysis using a Matrigel invasion model." (PMID 38003666, 2023). "CDH3 also has higher clinical tumor selectivity and safety scores in HNSC than existing targets (AUC = 0.92 and FDR p-value = 0.065; TS safety = 9.21; and HPA safety = 1.58)." (PMID 37835579, 2023). "Compared with adjacent non-tumor tissues, CDH3 protein expression was upregulated in CRC tissues, which is further confirmed by immunohistochemistry." (PMID 37151391, 2023). "The bispecific antibody PF-06671008, which targets CD3 on T cells and P-cadherin (CDH3) on tumor cells, is another promising strategy for T cell recruitment to tumor sites." (PMID 37680989, 2023). "Nonetheless, due to the favorable toxicity profile of the anti-CDH3 antibody and the interesting features of the target molecule, a radioimmunotherapy approach was proposed to achieve enhanced anti-tumor activity." (PMID 37760501, 2023). "Considering the consistent data in distinct models associating P‐cadherin with cell viability and GBM tumor growth in vivo, the influence of P‐cadherin silencing on cell cycle was also evaluated in our two GBM primary cultures with stable CDH3 knockdown." (PMID 34919784, 2022). "In CRC, silencing the CDH3 genes lead to a remarkable decrease in tumor cell viability and proliferation." (PMID 35114976, 2022). "CDH3 affected distinct cancer hallmarks in vitro and was related to increased tumor growth and shorter survival in vivo." (PMID 34919784, 2022). "Compared with normal samples, the expression level of CASP7, CDKN1B, EIG4G1, and EIF4EBP1 were significantly increased in the primary tumor samples, while that of CDH3 was significantly decreased." (PMID 35787690, 2022). "CDH3 was highly expressed in tumor samples, whereas high expression of CTGF, CYR61, OGN, FGF13, and CHRDL1 was associated with better prognosis and appeared to be a protective factor." (PMID 33816258, 2021). "Alterations of CDH3 can lead to tissue disruption, cell dedifferentiation, increased tumor cell aggressiveness, and ultimately metastasis." (PMID 34485109, 2021). "Among the hub genes, SLC2A1, CDH3 and EFHD2 increased across tumour stages and were associated with poorer survival probability, suggesting their critical roles in iCCA." (PMID 34013637, 2021). "Whereas CDH3 was significantly upregulated in THCA tissues and positively correlated with tumor stage, lymph node metastasis, sex, and age which indicated that CDH3 was an oncogene." (PMID 33816258, 2021). "Quantitative real-time RT-PCR showed increased CDH3 (P-cadherin) mRNA expression in tumor cells microdissected from a region with almost pure tubular elements." (PMID 32572153, 2020). "Re-analysis of TCGA gene expression data of another independent tumor cohort also supported activation of CDH3 (P-cadherin) mRNA expression in a subset of ILBC (4/70, 6%)." (PMID 32572153, 2020). "Tumor expression profile included an upregulation of basal cell markers such as Krt5, Krt6, Krt14 and Krt1 as well as Cdh3 and Cd44." (PMID 31779626, 2019). "CDH3 belongs to the family of classic cadherins that are engaged in various cellular activities including motility, invasion, and signaling of tumor cells, in addition to cell adhesion." (PMID 29364829, 2018). "With the exception of CDH3, there was strong staining for all the other basal markers in the tumor transplants." (PMID 30550540, 2018). "The basal/SCC‐like cases in the same consensus cluster showed almost no expression of FGFR3 and CCND1, whereas the reverse was seen for KRT5 and CDH3 tumour‐cell expression." (PMID 28195647, 2017).
tumor (continued). "The main purpose of this study was to conduct an expression survey of CDH3 in paired CRC tumor and normal colon mucosa samples and to determine the relationship between P-cadherin expression levels and cancer stage as well as preoperative plasma CDH3 levels." (PMID 29142905, 2017). "There was a positive correlation between tumor CDH3 QPCR and preoperative CDH3 blood levels (n=57, P= 0.038)." (PMID 29142905, 2017). "The muscle invasive tumour, however, showed a basal subtype (higher expression of CDH3, CD44, KRT5 and KRT6A) and likewise high aggressiveness (higher expression of KPNA2, BIRC5, CDC25B, COL4A1, and MSN)." (PMID 28916750, 2017). "Examples of tumor-related overexpressed genes which become promoter hypomethylated during carcinogenesis includes, but not limited to, Sonic Hedgehog, P-cadherin, and CDH3, as well as MATN4 and CTSL2, supporting the data reported here for BST-2." (PMID 25860442, 2015). "The alterations of EMT-associated markers, such as: loss of epithelial genes CDH1, CDH3 and gain of mesenchymal genes CDH2 and FN1, as well as the adoption of a migratory mesenchymal phenotype were maintained in all the tumor-derived cell lines." (PMID 25361000, 2014). "However, in cancer, CDH3 expression is often dysregulated, leading to altered adhesion properties that promote tumor progression and metastasis." (PMID 40227353, 2025). "Moreover, analysis of gene expression across pathological stages showed consistent upregulation of CDH1, CDH2, and CDH3 in advanced tumor stages, emphasizing the potential role of cadherin genes in NSCLC progression." (PMID 40860670, 2025). "Finally, two transmembrane proteins were identified as antigens: CDH3, an instrumental protein in modulating tumor cell metastasis and CD105, which is expressed on the endothelial cells of tumoral blood vessels and stroma and is associated with angiogenesis." (PMID 40432134, 2025). "Future research could explore changes in the expression of CDH3 and DNA methylation of CDH3 in chRCC to draw conclusions about potential correlations with the extensive atypia of chRCC and their tumor behavior." (PMID 40457272, 2025). "Taken together, these studies reaffirm our bioinformatics-based analysis and suggest that these extracellular matrix genes (CDH3, COL11A1, COL1A1, COL17A1, KRT19, ITGA2, LAMC2, and SULF1) are highly associated with PDAC tumor carcinogenesis and peritoneal metastasis." (PMID 39682235, 2024). "The strong association between CDH3 and CA72-4 implies that alterations in cell adhesion may contribute to the upregulation of CA72-4, potentially facilitating tumor spread." (PMID 39247592, 2024). "Moreover, HK2, MMP11, CDH3, PDK4, SERPINB5, and SLC2A1 expression were closely associated with tumour stages." (PMID 37234801, 2023). "Following dichotomization (into high- and low-stage or high- and low-grade tumors), CDH3 CGI hypermethylation was found to be associated with a higher tumor stage (low vs. high T; p = 0.0026; OR = 6.16 [1.99–21.60]) and higher tumor grade (low vs. high G; p = 0.0013, OR = 6.94 [2.26–24.41])." (PMID 38003666, 2023). "The result displayed that CDH3 expression increased with tumor progression." (PMID 37151391, 2023). "Compared to cells in tumor 3 that expressed increased epithelial markers like CDKN2A, CRB3, KRT13, and KRT6, tumor cells in metastatic LN exhibited high expression of mesenchymal markers like CDH3, ECM1, TGFB1, WARS, and VIM, indicating that tumor metastasis was related to EMT." (PMID 36569924, 2022). "However, CDH3 mRNA was also detectable in tumor cells microdissected from a region with conventional growth pattern, suggesting a regulation of P-cadherin expression at the mRNA and protein level." (PMID 32572153, 2020). "In contrast to the suppressor role of CDH1, CDH3 may act as an oncogene and stimulates a pro-invasive character of tumor cells in the presence of CDH1 resulting in a poor prognosis." (PMID 31105876, 2019).
tumor (continued). "We also identified a large number of cell adhesion and cell communication pathway genes, such as CDH3, SPP1, SPINK and CEACAM5 that are highly up-regulated in all lung AC tumours, and hence could be associated with the early metastasis of lung AC." (PMID 22369099, 2011). "However, high expression levels of CDH3 have been observed in various human tumor tissues." (PMID 39159001, 2024). "Several studies have demonstrated that aberrant P-cadherin expression is associated with cell proliferation and with tumors of the colon, breast, lung, thyroid, pancreas, and cervix, making P-cadherin (encoded by the gene CDH3) an excellent tumor-associated target." (PMID 37760501, 2023). "On the other hand, the expression of CDH3 showed significant and comparatively strong negative correlations with a number of microRNAs including hsa-miR-204, which is already known to show a strong association with invasive behaviors of tumor cells." (PMID 38003666, 2023). "Concordantly to the results obtained with the overexpression model, mice bearing CDH3‐low cells formed much smaller tumors than the ones injected with CDH3‐high cells, as observed by ultrasound imaging, both at two‐dimensional analyses and after three‐dimensional tumor reconstructions." (PMID 34919784, 2022). "Moreover, the oncogenic value of CDH3 is reinforced by the upregulation of CDH3‐positively correlated genes upon knockdown of RB and PTEN tumor‐suppressor genes, and by the association with HOXA9, a transcription factor with critical oncogenic functions in GBM." (PMID 34919784, 2022). "Our data suggest that CDH3 may be exerting tumor suppressive activities in PCa." (PMID 26771841, 2016). "Taking the signal CDH3 as an example, FOS is in general the dominant SSC that mediates the regulation of target genes; many tumor-related genes, including the keratins and S100 gene family, account for a substantial part of the most specific targets of CDH3." (PMID 40593827, 2025). "The results showed that the expression of IPCEF1, TFF3, GLT8D2, TPO and DIO1 were downregulated in the tumor group and DPP4, LRP4, CDH3, KCNJ2, CLDN1, GABRB2, FN1 were upregulated in the tumor group." (PMID 39513122, 2024). "The analysis revealed most cells in tumor microenvironment including stromal cell expressed EGFR, NFE2, and FSL1 genes while a lower number of cells expressed CDH3, ARL4D, and SH3RF2." (PMID 38172584, 2024). "Compared with serum tumor biomarkers CA24-2, CA19-9, CA72-4, and CEA in CRCs, CDH3 exhibited superior potential as a serum biomarker for monitoring chemotherapy response in distant metastatic CRCs." (PMID 39247592, 2024). "CDH3 was found to be highly expressed, while CTGF, CYR61, CHRDL1, OGN and FGF13 had significantly lower expression in tumor tissues compared with peri-tumor tissues." (PMID 33816258, 2021). "Taken together, these findings indicate that CDH3 and EFHD2 can activate these pathways to promote tumour progression." (PMID 34013637, 2021). "Key hub genes SLC2A1, CDH3 and EFHD2 showed increased expression across the tumour stage and were correlated with poor survival, whereas decrease of FAM171A1, ONECUT1 and PHYHIPL was correlated with better survival." (PMID 34013637, 2021). "Comparing with peri-tumor controls, the expression of CTGF, CYR61, CHRDL1, OGN and FGF13 were significantly decreased, whereas CDH3 significantly increased in PTC tissues which were consistent with the bioinformatics results obtained by TCGA dataset." (PMID 33816258, 2021). "As a result, we identified CDH3, EFHD2 as tumour‐promoting genes, and ONECUT1, PHYHIPL as tumour suppressing genes." (PMID 34013637, 2021). "Cadherin-3 (CDH3) regulates cell migration and tumor growth by interacting with cadherin-1 in PC and is upregulated during early-stage PC." (PMID 33173782, 2020).
tumor (continued). "MED30 induced the expressions of EMT-related genes (N-cadherin; CDH2, P-cadherin; CDH3, twist related protein 1 and 2; TWIST1/2, vimentin; VIM), but inhibited the expression of E-cadherin (CDH1) a known tumor suppressor." (PMID 26110885, 2015). "CDH3 expression was higher in C4 in LUAD, which may contribute to tumor progression and therapy resistance, while in C2 in LUSC, it could support tumor proliferation and resistance mechanisms." (PMID 40860670, 2025). "SinceMMTV-PyMT tumor organoids are epithelial-derived, and MDCK cells areepithelial origin, we expect that CDH3 may also regulate laminin-332,β-catenin, and phospho-FAK-associated signaling." (PMID 39007451, 2024). "Our analysis identified seven tumour suppressor genes (ITGA7, SLC45A1, TPPP, SCN4A, GIPR, SOGA3 and RAB6B) and six oncogenes (SAT1, SERPINE1, UPK2, SYT12, RASAL1 and CDH3) with significant false discovery rate (FDR)-adjusted P values (q-value) of less than 0.05." (PMID 38429478, 2024). "In this cohort, 75% of the tumours expressed CDH3, a feature that is acquired in tumours, as normal stomach epithelial cells do not express CDH3." (PMID 37372088, 2023). "While this, overall, suggests that changes in cadherin gene methylation and expression affect RCC tumor biology, the role of the chromosomal neighbor CDH3 is still not clear." (PMID 38003666, 2023). "Interestingly, CDH3 (r=-0.101, p=2.59E-02) and OGN (r=-0.104, p=2.09E-02) was negatively correlated with tumor purity." (PMID 33816258, 2021). "Increased nuclear expression of RB1 [RB1(N)↑], CDH3(C)↑-STK17A(N)↑ and FLNA(C)↑-KRAS(C)↑were associated with survival, but not independent of tumor stage, where C and N denote cytoplasm and nucleus, respectively." (PMID 33936170, 2021). "Among the hub genes, SLC2A1, CDH3 and EFHD2 displayed increased expression across the tumour stage." (PMID 34013637, 2021). "(F) Expression of the luminal markers, FOXA1 (1.8-fold increase) and GATA3 (1.8-fold increase), and the basal markers, CDH3 (6-fold decrease) and KRT6A (9-fold decrease) in tumor xenografts from mice treated with 5’-azacitidine compared to those of the vehicle control." (PMID 31036156, 2019). "The staining was positive in all tumors for all basal markers except CDH3, which showed no staining in any of the tumor samples." (PMID 30550540, 2018). "Although there was certain consistency in the alteration of CDH3 expression within the same tumor type, the directionality of the alterations was not preserved among the different tumor types." (PMID 26771841, 2016). "All 5 tumors with gain of CDH3 belonged to the HR+ type, and patients having a tumor with gain of CDH3 had worse RFS rates than patients without." (PMID 23679233, 2013). "Overall, 8 genes were identified as differentially expressed genes (DEGs) between GC tumor and nontumor tissues (eTable 9 in Supplement 1), with upregulated CDH3 and BAIAP2L2 and downregulated TMED6 also observed in advanced vs mild gastric lesions (eTable 11 in Supplement 1)." (PMID 38809553, 2024). "Also, CDH3 and OGN expression were positively correlated with tumor purity." (PMID 33816258, 2021). "Two main groups were identified, one over-expressing markers typically found in sporadic luminal tumours such as GATA3, TFF1 and SCUBE2, and the other negative for ESR1, ERBB2 and the PR gene (PGR) (triple negative) and over-expressing genes from the basal layer such as CDH3, CRYAB and KRT5-17." (PMID 19826428, 2009). "Our findings implicating P‐cadherin as a tumor promoting molecule, and the prognostic value of CDH3 independent of other known prognostic indicators, suggest this cell–cell adhesion molecule may be an attractive new therapeutic target for P‐cadherin‐positive tumors." (PMID 34919784, 2022). "While robust urothelial basal-cell stratification (CK5/EGFR/CDH3) typical of Uro tumors was absent, scattered CK5-positive cells were localized at the tumor-stroma interface, which is how more aggressive Urothelial-like tumors typically present." (PMID 40605119, 2025).